EGFR (epidermal growth factor receptor)
Diseases named in the same sentence as EGFR in open-access papers (continued):
Sharing a sentence is not in itself a finding about the gene and the disease.
mucormycosis (5 papers, 2018 to 2024). "Blocking EGFR with small molecule inhibitors reduces disease severity in mouse models of mucormycosis and oropharyngeal candidiasis." (PMID 39314401, 2024). "Blocking EGFR with small molecule inhibitors reduces disease severity in mouse models of mucormycosis and oropharyngeal candidiasis (9, –, 11)." (PMID 39475281, 2024). "In contrast, pulmonary mucormycosis is initiated via interaction of inhaled spores expressing CotH7 with integrin β1 receptor, which activates EGFR to induce fungal invasion of host cells." (PMID 32487760, 2020). "In contrast, pulmonary mucormycosis is initiated via interaction of inhaled spores expressing CotH7 with integrin α3β1 receptor, which activates EGFR to induce fungal invasion of host cells." (PMID 32487760, 2020). "We next sought to determine if EGFR signaling governs the establishment and/or progression of mucormycosis in a well-established in vivo murine model of mucormycosis." (PMID 30108171, 2018). "Of great clinical importance is our finding that inhibition of EGFR function by an FDA-approved drug ameliorates murine mucormycosis and is likely to represent a new therapeutic modality as adjunctive therapy to lethal mucormycosis." (PMID 30108171, 2018). "Furthermore, gefitinib treatment significantly prolonged survival of mice with pulmonary mucormycosis, reduced tissue fungal burden, and attenuated the activation of EGFR in response to pulmonary mucormycosis." (PMID 30108171, 2018). "Importantly, gefitinib, an FDA-approved drug that inhibits EGFR, protected mice from mucormycosis." (PMID 30108171, 2018). "This study enhances our understanding of how Mucorales fungi invade host cells during the establishment of pulmonary mucormycosis and provides a proof-of-concept for the repurposing of FDA-approved drugs that target EGFR function." (PMID 30108171, 2018).
myelodysplastic syndrome (5 papers, 2012 to 2023). A clonal hematopoietic disorder characterized by dysplasia and ineffective hematopoiesis in one or more of the hematopoietic cell lines. "One trial patient was diagnosed with myelodysplastic syndrome (MDS) about 3.5 years after completing 10 cycles on anti-EGFR-ILs-dox." (PMID 36879012, 2023). "Erlotinib was shown to decrease phosphorylation of JAK2 and STAT-5 in EGFR-negative myelodysplastic syndrome (MDS) cell lines KG-1 and erlotinib can disrupt signaling of the JAK2/STAT-5 pathway." (PMID 22436374, 2012).
peritoneal carcinoma (5 papers, 2019 to 2024). A peritoneum cancer that is located in the inside of the abdomen. "Cetuximab, a chimeric IgG1 monoclonal antibody that binds to the extracellular domain of EGFR, produced an objective response in 9 out of 26 patients when combined with carboplatin in patients with EGFR-positive ovarian or primary peritoneal cancer." (PMID 30646939, 2019).
renal dysfunction (5 papers, 2019 to 2024). "Within the FLAURA-ineligible patients, the most common exclusion criteria included cardiac risk factors, an inadequate performance status, less common EGFR mutations, and renal dysfunction, among others." (PMID 38539415, 2024). "The reference range of plasma selenium concentration is 40 to 200 μg/L in healthy adults, and our results revealed that the individuals carrying EGFR rs2280653 GG and GA genotypes might be susceptible to renal dysfunction beyond normal physiological selenium levels." (PMID 34501555, 2021). "EGFR was also significantly lower in renal dysfunction patients than other groups (P < 0.01)." (PMID 36129598, 2022).
respiratory failure (5 papers, 2014 to 2025). The significant impairment of gas exchange within the lungs resulting in hypoxia, hypercarbia, or both, to the extent that organ tissue perfusion is severely compromised. "A 75-year-old female with EGFR-mutant NSCLC developed respiratory failure with diffuse ground-glass opacities and profound lymphocytopenia (ALC 0.48×109/L)." (PMID 41479888, 2025). "Withdrawal of EGFR-TKI treatment is essential in all cases, and supportive treatments with oxygen supplementation are required in patients with respiratory failure." (PMID 33466795, 2021). "This study is also the first to review rescue or maintenance therapy with EGFR TKIs in non-squamous NSCLC patients with respiratory failure." (PMID 25050082, 2014). "The use of EGFR TKI as rescue or maintenance therapy during respiratory failure did not improve the rate of successful weaning (standard care 18% vs. with EGFR TKI, 22%; p = 0.81) in univariate and multivariate analyses." (PMID 25050082, 2014). "However, despite similar baseline clinical characteristics in the study groups during the period of respiratory failure, intake of EGFR TKIs as rescue or maintenance therapy does not lead to a better rate of weaning from the MV." (PMID 25050082, 2014).
staphylococcus aureus infection (5 papers, 2021 to 2025). An infectious process in which the bacteria Staphylococcus aureus is present. "EGFR activation by HB‐EGF prevents Staphylococcus aureus infection in human skin explants, possibly by increasing beta‐defensin‐3 secretion." (PMID 35538596, 2022). "In addition, the enriched KEGG pathways mainly contain focal adhesion, pancreatic secretion, thyroid hormone signaling pathway, staphylococcus aureus infection and ErbB (EGFR, epidermal growth factor receptor) signaling pathway." (PMID 35432454, 2022).
systemic sclerosis (5 papers, 2011 to 2025). A chronic disorder, possibly autoimmune, marked by excessive production of collagen which results in hardening and thickening of body tissues. "The hub gene analysis in CTD shows that EGFR has high scores in pulmonary arterial hypertension, connective tissue disease, and systemic sclerosis, and may be a key gene involved in the pathogenesis of SSc, especially SSc-PAH." (PMID 35663995, 2022). "Notably, in systemic sclerosis (SSc), TGF-β drives fibroblast transition via Smad signaling, whereas baricitinib’s EGFR affinity downregulates COL1A1/COL3A1 to restore collagen density in skin models." (PMID 41585231, 2025).
thoracic tumors (5 papers, 2020 to 2025). "A phase II trial showed a 96% local control rate for thoracic tumors using concurrent EGFR-TKIs and RT in advanced or metastatic NSCLC." (PMID 39772073, 2024). "Theoretically, EGFR-targeted NIR-PIT is applied to any type of cancer in which EGFR is overexpressed, and clinical trials are expected to progress in thoracic tumors." (PMID 35884975, 2022).
Thromboembolism (5 papers, 2019 to 2025). The formation of a blood clot inside a blood vessel that subsequently travels through the blood stream from the site where it formed to another location in the body, generally leading to vascular occlusion at the distant site. "The multivariate analysis also showed that more than one risk factor had more influence on thromboembolism than the use of VEGF or EGFR inhibitors." (PMID 37394446, 2023). "Altogether, both VEGF and EGFR inhibitors are risk factors for thromboembolism." (PMID 37394446, 2023). "However, a recent systematic review on biomarkers for prediction of thromboembolism in lung cancer demonstrated that D-dimer and epidermal growth factor receptor mutation were the most reproducible predictors of thromboembolism in this patient population." (PMID 31011294, 2019). "A cohort study revealed that the highest incidences of thromboembolism were observed in patients with ALK-mutant NSCLC (43.5%) followed by patients with EGFR-mutant cancers (21.2%) and wild-type cancers (17.2%)." (PMID 41426325, 2025). "Although the effects of EGFR inhibitors, a meta-analysis demonstrated a 1.34-fold increase in thromboembolism incidence in the drug group than that in the control group." (PMID 37394446, 2023). "In this study, the overall incidence of thromboembolism was twice as high in the EGFR inhibitor group, but the possibility of a beta error cannot be ruled out due to the limited number of cases." (PMID 37394446, 2023). "The occurrence of thromboembolism was the response variable, and VEGF or EGFR inhibitor administration was always included as an explanatory variable." (PMID 37394446, 2023). "Similarly, in the multivariate analysis of Model 1 and Model 2, the use of VEGF and EGFR inhibitors was not identified as a risk factor, whereas having at least one risk factor for thromboembolism was identified as a risk factor (P = 0.006, P = 0.006, respectively)." (PMID 37394446, 2023). "According to previous studies, patients on EGFR inhibitors, either cetuximab or panitumumab, are at higher risk of thromboembolism, especially with venous thromboembolism (VTE), than those not treated with EGFR inhibitors." (PMID 35954563, 2022). "The percentage of patients with a CV port was significantly higher in the EGFR-inhibitor group than in the VEGF-inhibitor group (P < 0.001); however, the other parameters, including the risk factor scores for thromboembolism in cancer patients, did not significantly differ between the groups." (PMID 37394446, 2023).
toxoplasmosis (5 papers, 2018 to 2025). A parasitic disease contracted by the ingestion or fetal transmission of toxoplasma gondii. "In this regard, expression of EGFR in normal adult neural tissue (the main site affected in toxoplasmosis) is moderate and restricted to areas such as the EGF subventricular zone." (PMID 39869638, 2025). "In terms of signaling pathways, DSThighM macrophages and hepatocytes exhibited high activity in Toxoplasmosis, Th17 cell differentiation, and EGFR tyrosine kinase inhibitor resistance." (PMID 38235128, 2023). "A combination of low-dose EGFR TKI with antibiotics may lead to an improved regimen against toxoplasmosis." (PMID 34179003, 2021). "However, EGFR expression is limited in the brain and retina, organs affected in toxoplasmosis." (PMID 39869638, 2025). "In addition, EGFR is expressed in various non-hematopoietic cells as well as microglia further supporting the possibility that administration of EGFR tyrosine kinase inhibitors may assist in the treatment of toxoplasmosis." (PMID 30679495, 2019).
venous thromboembolism (5 papers, 2017 to 2024). Occlusion of the lumen of a vein by a thrombus that has migrated from a distal site via the blood stream. "Lots of research had provided evidence of venous thromboembolism incidence in EGFR mutation patients and lead to an inconsistent conclusion." (PMID 35814445, 2022). "Last, but not least, the low rates of venous thromboembolism in the PALOMA trial underlines the importance of personalized risk evaluation as a baseline and prompt administration of anticoagulants in patients with EGFR-mutant NSCLC." (PMID 39336976, 2024).
vitiligo (5 papers, 2018 to 2025). Generalized well circumscribed patches of leukoderma that are generally distributed over symmetric body locations and is due to autoimmune destruction of melanocytes. "Tyrosine kinases (e.g., EGFR, Kit receptor) regulate melanocyte function and melanin synthesis.EGFR: Promotes melanocyte proliferation and melanin production (target for hyperpigmentation disorders).Kit: Key in melanocyte survival; linked to pigmentary disorders (e.g., vitiligo)." (PMID 40536117, 2025).
vulvar squamous cell carcinoma (5 papers, 2003 to 2023). An invasive squamous cell carcinoma arising from the vulva. "Recently, in head and neck and vulvar squamous cell carcinoma, EGFR mutations and protein overexpression were predominantly HPV-negative and associated with poorer prognoses." (PMID 20459770, 2010). "Coadministration of gefitinib potentiated the antitumour effect of radiation on A431 cells (human vulvar squamous-cell carcinoma cells that express high levels of EGFR) both in vitro and in vivo." (PMID 14661048, 2003).
anaplastic cancer (4 papers, 2005 to 2020). "All these evidences strongly support the great potential of using EGFR CRISPR/Cas9 system to inhibit the malignancy in anaplastic cancer cells." (PMID 29849821, 2018). "EGFR was universally expressed in anaplastic cancer cell lines at a variety of levels." (PMID 15785737, 2005).
ataxia telangiectasia (4 papers, 2014 to 2023). Ataxia-telangiectasia is the association of severe combined immunodeficiency (affecting mainly the humoral immune response) with progressive cerebellar ataxia. "WSE correlated with mutations in the genes SMARCB1 (p=0.002), Ataxia telangiectasia mutated (p=0.004), Kinase Insert Domain Receptor (p=0.006), and were borderline significant in RET and EGFR exon." (PMID 30093964, 2018).
Candida infection (4 papers, 2009 to 2025). "This analysis of signal transduction events in esophageal Candida infection demonstrated a potential functional interaction of epithelial cells with PMNs and that EGFR, NF-κB and MAPK/AP-1 are involved in divergent signalling events governing hBD-2 and hBD-3 expression." (PMID 19523197, 2009).
celiac disease (4 papers, 2011 to 2023). An autoimmune genetic disorder with an unknown pattern of inheritance that primarily affects the digestive tract. "The mechanism involves epidermal growth factor receptor (EGFR) activation, and its pathogenetic relevance is illustrated by the finding that gliadin toxicity in celiac disease includes intestinal release of zonulin and EGFR activation." (PMID 25184418, 2014). "This could, in turn, prolong EGFR activation and increase cell proliferation in crypt enterocytes, which is one of the features of the mucosal lesion typical of celiac disease." (PMID 37685847, 2023).
cerebrovascular disease (4 papers, 2019 to 2024). "For either EGFR mutation positive or wild-type patients with cerebrovascular disease is associated with a higher risk of death." (PMID 31419239, 2019).
chronic atrophic gastritis (4 papers, 2012 to 2023). Atrophic gastritis that is persistent and long-standing. "The transactivation of epidermal growth factor receptor (EGFR) is strongly linked to H. pylori infection, gastric epithelial hyperplasia, and gastric atrophy." (PMID 22936949, 2012).
cognitive decline (4 papers, 2020 to 2025). "The results revealed substantial inhibition of the EGFR/PI3K/Akt signaling pathway in the context of the cognitive decline caused by surgery." (PMID 39781463, 2025). "In this context, exploring structural changes in patients’ brains before and after EGFR-TKI treatment could help in determining the causes of cognitive decline." (PMID 33489880, 2020). "Even though EGFR is extensively known and studied for its involvement in cancers, studies have shown that EGFR inhibitors are a feasible therapeutic option to reduce cognitive decline in AD." (PMID 38275516, 2024). "Moreover, Lingo1 upregulation in hippocampal neurons inhibited the PI3K/Akt signaling pathway by decreasing EGFR levels, which further promoted cognitive decline after anesthesia and surgery by increasing neuronal apoptosis." (PMID 39781463, 2025). "Moreover, upregulated Lingo1 in hippocampal neurons contributed to cognitive decline after surgery through activating the RhoA/ROCK1 signaling pathway and inhibiting the EGFR/PI3K/Akt signaling pathway." (PMID 39781463, 2025). "However, during routine follow-ups, patients with NSCLC undergoing EGFR-TKI treatment in our department, the Oncology Department of West-China Hospital, have reported cognitive decline after starting EGFR-TKI treatment, a side effect that has not previously been reported." (PMID 33489880, 2020).
congenital mesoblastic nephroma (4 papers, 2018 to 2025). A low grade childhood congenital malignant neoplasm arising from the kidney. "Instead of gene fusions, a small subset of these tumors in soft tissues or kidneys (in the latter site a traditional name congenital mesoblastic nephroma is often used) may harbor activating EGFR or BRAF point mutations." (PMID 39387892, 2024). "Interestingly, EGFR‐KDD was initially identified in classic or mixed variants of congenital mesoblastic nephroma (CMN), which are composed of myofibroblasts in fascicular pattern and may display nests of benign cartilage." (PMID 40178433, 2025). "The presence of the EGFR ITD confirmed a diagnosis of congenital mesoblastic nephroma." (PMID 37686670, 2023). "Here, the authors investigate the genetic basis of cryptogenic congenital mesoblastic nephroma and infantile fibrosarcoma lacking the canonical NTRK3-ETV6 fusion gene, and identify therapeutically tractable intragenic rearrangements in EGFR and BRAF." (PMID 29915264, 2018).
cystitis (4 papers, 2009 to 2022). Inflammation of the urinary bladder. "EGFR IHC staining was able to differentiate between dogs with MIUC and polypoid cystitis (p < 0.001) with a sensitivity of 72% and specificity of 100%." (PMID 34680588, 2021).
eczema (4 papers, 2014 to 2024). "Prior case reports have identified xerotic eczema beneath purpuric eruptions, underscoring the need for moisturizers to support skin barrier function during EGFR inhibitor therapy." (PMID 39881923, 2024).
encephalitis (4 papers, 2019 to 2024). An acute inflammatory process affecting the brain parenchyma. "Expression in endothelial cells of a DN EGFR that inhibits EGFR signaling led to a decrease in T. gondii invasion of the brain and retina as well as diminished development of encephalitis and retinitis." (PMID 30679495, 2019). "In addition, EGFR activation is crucial for viral entry during HSV-1 infection, which causes a wide range of symptoms from skin lesions to deadly encephalitis." (PMID 33996800, 2021).
endometrial stromal sarcoma (4 papers, 2010 to 2017). "Approximately 70% of low grade endometrial stromal sarcomas also expresses epidermal growth factor receptor (EGFR; HER1)." (PMID 20368795, 2010). "Up to 70% of low-grade endometrial stromal sarcomas showed positive reactions for EGFR which led to the interesting suggestion that this may provide the basis for a new therapeutic strategy using monoclonal antibodies against EGFR." (PMID 24146786, 2013). "In addition, EGFR expression has been described in approximately 70% of endometrial stromal sarcomas." (PMID 20368795, 2010).